CXCL8 (C-X-C motif chemokine ligand 8)
Diseases named in the same sentence as CXCL8 in open-access papers (continued):
Sharing a sentence is not in itself a finding about the gene and the disease.
urothelial carcinoma (7 papers, 2018 to 2025). A malignant neoplasm derived from the transitional epithelium of the urinary tract (urinary bladder, ureter, urethra, or renal pelvis). "This study aimed to investigate and clarify the tumour-promoting role of CXCL8 secreted by TAMs in the urothelial carcinoma microenvironment of the bladder." (PMID 32201645, 2020). "Furthermore, a study investigating the role of CXCL8 secreted by TAMs in urothelial carcinoma showed the infiltration of TAMs in the tumour microenvironment led to the elevation of CXCL8, which in turn promoted the secretion of MMP-9, VEGF, and E-cadherin by BC cells." (PMID 37052868, 2023).
uveal melanoma (7 papers, 2007 to 2023). A melanoma derived from melanocytes of the uveal tract. "All 5 human uveal melanoma cell lines were shown to produce significant levels of CXCL8, CXCL1, and HGF." (PMID 17261188, 2007). "To verify our computational findings, we tested the mRNA expression level of CCL18, CXCL8, GTPBP1, JAG2, PRELID1 and PTGER4 in uveal melanoma cell lines: M17, M23 and SP6.5 and normal uveal epithelial cell: Um95." (PMID 36597071, 2023). "All 5 human uveal melanoma cell line cytospins stained positive for CXCL1, CXCL8, and their receptors CXCR2 and CXCR1 respectively." (PMID 17261188, 2007). "In conclusion, characterizing the expression of CXCL12, CXCL8, CXCL1, and HGF in uveal melanoma cell lines leads us to a better understanding of how these cytokines are integral in the metastatic process." (PMID 17261188, 2007). "The aim of this study was to characterize the presence and roles of CXCL12, CXCL8, CXCL1, and HGF in five human uveal melanoma cell lines, using different methods, in order to ascertain their significance in this disease." (PMID 17261188, 2007). "The migratory ability of the 5 human uveal melanoma cell lines was positively influenced by the four chemotactic factors tested, namely CXCL12, CXCL8, CXCL1, and HGF." (PMID 17261188, 2007). "The present study was designed in order to analyze the expression of CXCL12, CXCL8, CXCL1, and HGF in five human uveal melanoma cell lines (92.1, SP6.5, MKT-BR, OCM-1, UW-1) and to investigate the effects of these factors on the migratory ability of the 5 cell lines." (PMID 17261188, 2007). "Demonstration of a functional role for CXCL12, CXCL8, CXCL1, and HGF in uveal melanoma may yield novel therapeutic targets." (PMID 17261188, 2007).
Abdominal obesity (6 papers, 2017 to 2025). Excessive fat around the stomach and abdomen. "Among them, adiponectin, leptin, TNF-α, Factor D (adipsin), lipocalin-2 (NGAL), Serpin E1 (PAI-1), and CXCL8 (IL-8) were confirmed to have a positive correlation with central obesity (defined as WC)." (PMID 36768360, 2023).
acute liver failure (6 papers, 2006 to 2022). Rapid deterioration of liver function causing encephalopathy and coagulopathy. "Notably, studies have reported that CXCL8 levels are elevated in the serum of patients with ACLF or acute liver failure; in fact, the levels of CXCL8 significantly correlate with the serum levels of total bilirubin, and are significantly associated with high MELD scores and short-term mortality." (PMID 33968135, 2021). "CCL11 (Eotaxin) was selectively increased in biliary atresia patients, while IL-3, IL-6, CXCL8 (IL-8), IL-9, IL-16, MIF, CCL4 (MIP-1 β), and CXCL1 (GRO-α), were increased in both biliary atresia and acute liver failure." (PMID 30740106, 2019).
allergic contact dermatitis (6 papers, 2017 to 2023). An inflammatory skin condition caused by an immune response to direct contact between the skin and an allergen. "The initial response to ticks suggested by this study is similar to an allergic contact dermatitis that is elicited by keratinocytes and fibroblasts producing IL-6, CXCL-8 and CCL-2 to recruit inflammatory leukocytes." (PMID 28143523, 2017). "Furthermore, CBD can elicit anti-inflammatory effects in an allergic contact dermatitis model, where CBD treatment resulted in an elevation in the levels of AEA, and also blocked the increase of IL-6, CXCL8, TNF-α, MCP-2 in polyinosinic-polycytidylic acid-stimulated HaCaT keratinocytes." (PMID 37680639, 2023).
bone marrow fibrosis (6 papers, 2020 to 2025). "Elevated CXCL8 levels were reported in pulmonary and bone marrow fibrosis and were associated with disease progression." (PMID 40981201, 2025).
contact dermatitis (6 papers, 2016 to 2026). An inflammatory skin condition caused by direct contact between the skin and either an irritating substance or an allergen. "Dermal fibroblasts participate in contact dermatitis by sensing irritants and allergens through TLRs and other receptors, subsequently producing inflammatory mediators (IL-1, IL-6, IL-8, TNF-α, CCL2, CCL5, CXCL1, CXCL8) that recruit and activate T cells and innate immune cells." (PMID 41598494, 2026).
cutaneous leishmaniasis (6 papers, 2012 to 2024). Leishmaniasis affecting the skin. "The aim of the present study was to determine single nucleotide polymorphisms of IL-1β (−511), CXCL8 (−251) and IL-1RA (+2018) in patients with cutaneous leishmaniasis infected with Leishmania mexicana." (PMID 22629474, 2012). "In addition, both miR146a rs2910164 and miR499a rs3746444 can influence the expression of CXCL8 and were associated with the development of cutaneous leishmaniasis caused by leishmania guyanensis." (PMID 38807156, 2024). "Even though elevated levels of mRNA IL-1β have been reported in biopsies of patients with American cutaneous leishmaniasis, neither IL-1β (−511), CXCL8 (−251) nor IL-1RA (+2018), have been associated with disease in leishmaniasis." (PMID 22629474, 2012).
epithelial dysplasia (6 papers, 2012 to 2025). "Data showed that there was almost no CXCL8 secretion with fewer BMSCs (CD105‐positive cells) in the normal oral epithelial cells, and there were a little more CXCL8 secretion and BMSCs around blood vessels (co‐localization shown in orange colour) in the epithelial dysplasia." (PMID 32588946, 2020).
Graves disease (6 papers, 2016 to 2026). Graves' disease is an autoimmune disorder that leads to overactivity of the thyroid gland (hyperthyroidism).It is caused by an abnormal immune system response that causes the thyroid gland to produce too much thyroid hormones. "More recent studies demonstrated that iodide positively regulates the expression of the CXCL8 gene and that TSH induces the production of CXCL8 in Graves’ disease derived peripheral blood fibrocytes expressing the TSH receptor." (PMID 29977225, 2018).
Hodgkins lymphoma (6 papers, 2015 to 2022). A heterogeneous group of malignant lymphoid neoplasms of B-cell origin characterized histologically by the presence of Hodgkin and Reed-Sternberg (HRS) cells in the vast majority of cases. "CXCL8 is upregulated in many cancers including solid tumors (brain, breast, colon, gastric, lung, and others) and blood cancers (AML, CLL, Hodgkin’s lymphoma) and high levels of CXCL8 expression are often linked with disease progression." (PMID 30185911, 2018).
kidney cancer (6 papers, 2018 to 2025). Primary or metastatic malignant neoplasm involving the kidney. "Thus, high CXCL8 levels are associated with the presence of different cancers (oesophageal, gastric, pancreatic, breast, and kidney cancer), metastasis, and drug resistance." (PMID 40076892, 2025). "CXCL8 has been found to be higher in the serum of patients with oesophageal, gastric, pancreatic, breast, or kidney cancer." (PMID 40076892, 2025). "In experimental kidney cancer in mice, anti-VEGFA accelerates tumor growth but when combined with an anti-CXCL8 antibody, tumor growth is inhibited." (PMID 37508458, 2023). "Kidney cancer cells overexpress several redundant pro-angiogenic factors, including VEGFA and the cytokine CXCL8, compared to healthy tissues." (PMID 37508458, 2023).
myositis (6 papers, 2014 to 2025). "According to our results, the elevated cytokines found in the myositis seronegative patients (IL-6, IL-23, IL-12p70, IL-33, and CXCL8) are related to a Th17 profile." (PMID 39456842, 2024). "We found higher serum levels of IL-10, IL-6, CXCL8, IL-1β, IL-33, IFN-γ, TNF-α, IL-23, and IL-17A in myositis patients compared to the HSs." (PMID 39456842, 2024). "In particular, chemokines, a class of small cytokines with potent chemotactic activity, such as IL-8 (CXCL8), Mig (CXCL9), IP-10 (CXCL10), RANTES (CCL5), and MCP-1 (CCL2), are overexpressed during myositis in infiltrating inflammatory cells, extracellular matrix, and muscle fibers." (PMID 24895631, 2014).
pneumococcal meningitis (6 papers, 2006 to 2026). An acute purulent infection of the meninges and subarachnoid space caused by Streptococcus pneumoniae, most prevalent in children and adults over the age of 60. "In an infant rat model of pneumococcal meningitis a serotype 3 strain (P21) is often used to induce the disease and here we have shown that in vitro, following antibiotic lysis, which would release the pneumolysin, liposome treatment greatly reduced CXCL8 levels from the epithelial cells." (PMID 27430279, 2016). "Patients with pneumococcal meningitis show high levels of pro-inflammatory cytokines such as TNF-α, IL-1β, IFN-γ, IL-2, IL-6 and IL-12, anti-inflammatory cytokines (IL-10 and TGF-β) and chemokines such as CXCL8 (IL-8) CCL3 (MIP-1a) and CCL2 (MCP-1) in their CSF." (PMID 26744349, 2016).
Pruritus (6 papers, 2015 to 2025). Pruritus is an itch or a sensation that makes a person want to scratch. "The aim of the study was to analyse serum concentrations of CCL2/MCP-1, CCL3/MIP-1α, CCL4/MIP-1β, CCL5/RANTES, CCL17/TARC, CCL18/PARC, CCL22/MDC and CXCL8/IL-8, and their correlation with PsO severity and pruritus intensity." (PMID 36362116, 2022). "Among the studied chemokines (C-C Motif Chemokine Ligand (CCL) 2/MCP-1, CCL3/MIP-1α, CCL4/MIP-1β, CCL5/RANTES, CXCL8/IL-8, CCL17/TARC, CCL18/PARC, CCL22/MDC), only CCL17/TARC showed a positive correlation with pruritus intensity." (PMID 37834183, 2023).
renal fibrosis (6 papers, 2016 to 2024). A final common manifestation of a wide variety of chronic kidney diseases characterized by glomerulosclerosis and tubulointerstitial fibrosis. "Interestingly, the CXCL8 antagonist G31P has been shown to improve renal fibrosis by reducing ECM, which may be associated with improved expression of MMP-2 and MMP-9." (PMID 37287620, 2023). "In an in vivo study, deletion of microRNA‐146a, which regulates CXCL8 secretion in tubular cells, promoted the development of tubular lesions and renal fibrosis after AKI as a result of an uncontrolled cytokine storm." (PMID 38923445, 2024).
sarcoma (6 papers, 2013 to 2025). A usually aggressive malignant neoplasm of the soft tissue or bone. "Children with sarcomas have increased blood CXCL1 levels compared to healthy individuals, although a much greater increase occurs in CXCL8/IL-8, whose high blood levels are associated with a poorer prognosis for patients with sarcomas." (PMID 38673949, 2024).
trachoma (6 papers, 2008 to 2024). "Chemokine protein levels for CCL11 (Eotaxin), CXCL8 (IL-8), CXCL9 (MIG), and CCL2 (MCP-1) were elevated in chronic scarring trachoma compared with age and sex matched controls (P<0.05, for all)." (PMID 18628987, 2008).
urothelial bladder cancer (6 papers, 2012 to 2024). "A high expression of CXCL8 was found to be a poor prognostic factor of urothelial bladder cancer." (PMID 23800251, 2013).
Arthralgia (5 papers, 2021 to 2025). "Furthermore, CXCL8 has also been detected in serum and synovial fluid of patients with chronic arthralgia after CHIKV infection." (PMID 34659240, 2021).
autoimmune thyroid disease (5 papers, 2015 to 2023). Inflammatory disease of the thyroid gland due to autoimmune responses leading to lymphocytic infiltration of the gland. "Initially, CXCL8 was hypothesized to play a role in the development of autoimmune thyroid diseases." (PMID 29977225, 2018).
biliary atresia (5 papers, 2017 to 2025). A rare, biliary tract disease characterized by progressive obliterative cholangiopathy of the intra- and extrahepatic bile ducts, occurring in the embryonic/ perinatal period, leading to severe and persistent neonatal jaundice and acholic stool. "Circulating CXCL8/IL-8-expressing B cells, which are considered proinflammatory, are found in the peripheral blood of biliary atresia patients." (PMID 40595432, 2025). "In addition, the hepatic IL8/Cxcl8 gene expression is increased at the time of diagnosis of biliary atresia above the levels seen in age-matched subjects with other causes of neonatal cholestasis." (PMID 28763485, 2017).
cervical squamous cell carcinoma (5 papers, 2017 to 2025). A squamous cell carcinoma arising from the cervical epithelium. "The data showed a significant increase in IDO1, CXCL1, and CXCL8 mRNA expression in cervical squamous cell carcinoma and endocervical adenocarcinoma (CECS)." (PMID 37626777, 2023). "A prognostic nomogram integrating three molecular markers (EFNA1, CXCL8, PPP1R14A) with clinicopathological parameters (age, TNM stage) was developed to predict 3-/5-/8-year overall survival in cervical squamous cell carcinoma." (PMID 40406253, 2025). "Time-dependent ROC analysis evaluated the prognostic accuracy of a three-gene signature (EFNA1, CXCL8, PPP1R14A) for cervical squamous cell carcinoma survival outcomes." (PMID 40406253, 2025). "In another example, cervical squamous cell carcinoma and endocervical adenocarcinoma exhibited a negative correlation between the expression of CXCL1, CXCL6, and CXCL8 and EMT, whereas the expression of CXCL3, CXCL5, and PPBP positively correlated with EMT." (PMID 37686093, 2023).
clear cell renal cell carcinoma (5 papers, 2019 to 2026). "Analysis of The Cancer Genome Atlas (TCGA) kidney clear cell carcinoma (KIRC) database for RNA sequencing data related to ccRCC showed significantly reduced overall survival in high expressers of CXCL8 (IL8), CCL5, CSF2, TFPI-2, and SERPINE1 (PAI1)." (PMID 35886951, 2022).
Cough (5 papers, 2010 to 2025). A sudden, audible expulsion of air from the lungs through a partially closed glottis, preceded by inhalation. "The poly(I:C)-induced release of inflammatory mediators, including CXCL8, interleukin (IL)-6 and CXCL1, from ASMCs from cough patients was significantly impaired compared with healthy non-cough subjects." (PMID 28842514, 2017).
exanthema (5 papers, 2012 to 2024). "Interestingly, the sera from ZIKV-infected women that presented with exanthema showed higher levels of CXCL8 (23.37 vs. 9.95 pg/mL)." (PMID 33430059, 2021).
fungal keratitis (5 papers, 2015 to 2023). "MATR3 (AUC = 0.95), CXCL9 (AUC = 0.95), and KCNA3 (AUC = 0.90) were among the best candidate markers for viral keratitis, and S100A8 (AUC = 1), CXCL8 (AUC = 1), and CCL20 (AUC = 1) were among the best candidates for bacterial/fungal keratitis." (PMID 38274739, 2023). "We identified 60 viral genes and 327 bacterial/fungal genes with an AUC of at least 0.9, among them MATR3, CXCL9, and KCNA3 for viral keratitis, and S100A8, CXCL8, and CCL20 for bacterial/fungal keratitis." (PMID 38274739, 2023).
gallbladder cancer (5 papers, 2012 to 2022). "In addition to malignant cells, cells in TME can also secret CXCL8 and promote cancer cell proliferation, which can be supported by a recent study that suggested that CAFs in TME can release CXCL8 to increase the proliferation ability of gallbladder cancer cells." (PMID 35372515, 2022).
interstitial cystitis (5 papers, 2015 to 2023). A rare chronic debilitating urogenital disease characterized by urinary frequency, urgency, and pelvic pain. "The core genes (CXCL8, CXCL1, IL6) obtained in this study may be potential biomarkers of interstitial cystitis with guiding significance for clinical treatment." (PMID 33848079, 2021).
Kaposi's sarcoma (5 papers, 2004 to 2025). A malignant neoplasm characterized by a vascular proliferation which usually contains blunt endothelial cells. "As CXCL1 and CXCL8/IL-8 are angiogenic factors, they play an important role in the early stages of Kaposi’s sarcoma, particularly in the development of its angiogenic phenotype." (PMID 38673949, 2024).
meningioma (5 papers, 2011 to 2022). A generally slow growing tumor attached to the dura mater. "K-M survival analysis revealed that CXCL8 and MYC were associated with prognosis of meningioma patients." (PMID 34772393, 2021). "The results showed yellow modules are negatively related to the degree of infiltration of resting mast cells in meningioma tissues, thus, genes such as MYC, CXCL2, CXCL8 and FOSL1 in the module, are inversely associated with the degree of mast cell infiltration." (PMID 34772393, 2021). "Hence, we speculate that the key genes, including MYC and CXCL8, are involved in meningioma progression via the regulating of different pathways such as the TNF signaling pathway, cytokine-cytokine receptor interaction, and IL-17 signaling pathway." (PMID 34772393, 2021). "Similarly, it has been found that CXC receptor activates ERK1/2 and stimulates meningioma cell proliferation, and in systematic investigation of quercetin for cardiovascular disease treatment, CXCL8 is enriched in the TNF signaling and IL-17 signaling pathways." (PMID 34772393, 2021). "DEGs of MYC and CXCL8, miRNAs of miR-29c-3p and miR-145-5p, as well as pathways such as the TNF signaling pathway, cytokine-cytokine receptor interaction, and IL-17 signaling pathway, probably involved in meningioma development, were obtained." (PMID 34772393, 2021). "Moreover, based on the COX univariate and multivariate regression analyses showed CXCL8 and MYC might be prognostic biomarkers for meningioma patients." (PMID 34772393, 2021).
metastatic prostate carcinoma (5 papers, 2012 to 2020). A carcinoma that arises from the prostate gland and has spread to other anatomic sites. "In one instance, increased CXCL8 expression has been linked with markedly diminished AR levels and the generation of a more aggressive disease in both primary as well as metastatic prostate cancer." (PMID 32585812, 2020). "There appears to be a positive correlation between transcriptional expression of angiogenic factors (including CXCL8) and metastatic prostate cancer." (PMID 32585812, 2020). "The current study was undertaken to characterize the effect of anti-metabolites on inducing CXCL8 signaling and determining whether the constitutive and/or drug-induced CXCL8 signaling in metastatic prostate cancer (CaP) cells modulates their sensitivity to this class of agent." (PMID 22590561, 2012).
relapsing-remitting MS (5 papers, 2017 to 2026). "In our study we hypothesized that serum concentrations of CCL20, CXCL8 and CXCL0 are induced in patients with relapsing-remitting MS (RRMS) in comparison to healthy individuals, and that they are associated with EBV infection." (PMID 39125633, 2024).
urticaria (5 papers, 2014 to 2025). A vascular reaction of the skin characterized by erythema and wheal formation due to localized increase of vascular permeability. "For example, CCL5/RANTES, CCL2/MCP-1, and CXCL8/IL-8 are able to induce histamine and serotonin release by mast cells, suggesting their contribution to the development of urticaria by a direct effect on mast cell degranulation." (PMID 29038618, 2017).
uterine disease (5 papers, 2014 to 2025). "The use of recombinant CXCL8 as an immunomodulator constitutes a new attempt to treat and prevent uterine diseases." (PMID 34206536, 2021).
allergic conjunctivitis (4 papers, 2017 to 2023). "DS70 dose-dependently reduced clinical aspects of allergic conjunctivitis, conjunctival mast cell and eosinophil infiltration, α4 integrin expression, and levels of mRNAs for IL-1β, IL-8 (CXCL8), CCL5, and CCL11, thus representing an alternative to antihistamines and mast cell-stabilizing agents." (PMID 32854363, 2020).